TNF (tumor necrosis factor)
Diseases named in the same sentence as TNF in open-access papers (continued):
Sharing a sentence is not in itself a finding about the gene and the disease.
infection (continued). "Notably, at 48 h post-infection, both berbamine and tetrandrine significantly reduced TNF-α levels by around 37% and 81% respectively, while the inhibitory effect of tetrandrine was greater (p < 0.05)." (PMID 38664855, 2024). "Mice lacking Fas or FasL showed decreased expression of CXCL10 and TNF-α at day 9 post-infection." (PMID 39339840, 2024). "In addition, homozygous CC genotypes for rs1799964 (TNF) were associated with higher CD8+ and lower CD4+ T-cell counts compared to some individuals with HIV mono-infection group." (PMID 39066175, 2024). "In accordance with the relevant pathological changes, the selected proinflammatory cytokines, including IL-1β, IL-6, and TNF-α, in the infected mice were obviously elevated at 1–3 days post-infection and then maintained a slight upregulation at lower levels at 5 and 7 days post-infection." (PMID 38338106, 2024). "We identify TNF signaling as a major driver of Tim3 expression in NK cells during infection." (PMID 39543125, 2024). "The data suggest a dual role for ISG15 in modulating the immune landscape in DM, in terms of M1 macrophages, when the infection or inflammation is severe enough to affect an organ, macrophages first exhibit the M1 phenotype to release TNF-α, IL-1β, IL-12, and IL-23 against the stimulus." (PMID 39559355, 2024). "The mock infection resulted in low levels of TNF (15.2 +/− 2.0 pg/mL) at 5 dpi." (PMID 39459974, 2024). "Moreover, increased expression of genes encoding for the pro-inflammatory cytokines TNF, IL-1β, and IFN-γ was detected in heart samples obtained from the infected group compared to uninfected controls 6 or 12 months after infection." (PMID 39136016, 2024). "The cytometric bead array results showed that the R77Q mutation resulted in a lower expression of TNF when compared to that of WT, but there was no statistical difference between Null and R77Q (89.3 vs. 57.3 pg/mL respectively; p = 0.07) infection." (PMID 39459974, 2024). "During initial infection, the ingestion of merozoites and fragments by macrophages or the presence of antigen-presenting trophozoites in the circulation or spleen leads to the release of tumor necrosis factor-alpha (TNF-α)." (PMID 38656731, 2024). "The GPNMB functions to reduce inflammation by increasing anti-inflammatory cytokines like IL10 and decreasing proinflammatory cytokines like TNFα, IL-6, and IL-12, which aid in response to lesions in the tissue or infection, and can be triggered by pathogens that are present in their environment." (PMID 39744066, 2024). "Macrophages, derived from monocytes, are pivotal in engulfing pathogens and dead cells through phagocytosis while also releasing pro-inflammatory cytokines like interleukin-1 (IL-1), IL-6, and tumor necrosis factor-alpha (TNF-α) to recruit additional immune cells to sites of infection." (PMID 39518533, 2024). "Although both T. forsythia stimuli induced the production of pro-inflammatory mediators of a similar magnitude, T. forsythia ΔhtrA infection resulted in significantly higher levels of TNF-α and significantly lower levels of MCP-1 compared to infection with the T. forsythia wild-type." (PMID 39035711, 2024). "Therefore, we examined the expression of cytokine genes (IL-1β, IL-6, IL-10, TNF-α, and GM-CSF) after infection." (PMID 38903792, 2024). "TNF-α serves as a proinflammatory indicator, whereas iNOS acts as a proinflammatory and oxidative stress marker, and these proinflammatory cytokines attract inflammatory cells to the site of infection." (PMID 39619935, 2024). "In the present work, it was also observed that infection of mice with a UPEC strain activated the expression of TNF-α; however, the administration of a polyvalent bacterial lysate (UNAM-HIMFG) controlled both colonization and inflammation (activating the expression of IL-10) of the tissues." (PMID 39337365, 2024). "IL1β and TNFα are important pro-inflammatory cytokines involved in host defense against infection." (PMID 39203441, 2024).
infection (continued). "Thus, it was reported that azurocidin and lactoferrin produced by neutrophils during infection induce the polarization of MACs to a proinflammatory M1 phenotype, characterized by TNFα and interferon (INF)γ release and enhanced phagocytosis." (PMID 38334600, 2024). "ICAM-1 is a glycoprotein constitutively present on the surface of various cells, including epithelial and endothelial cells, lymphocytes, and monocytes; an upregulation in response to specific stimuli, such as injury or infection, is mediated by cytokines (TNF-α, IFN-γ) or ROS." (PMID 38892239, 2024). "However, a retrospective study directly comparing anti-TNF and vedolizumab in elderly patients did find vedolizumab treated patients to have fewer infection-related hospitalizations compared to patients treated with anti-TNF." (PMID 38256499, 2024). "The results indicated a significant increase in the mRNA and protein expression levels of the inflammatory cytokines IL-6, IL-10, and TNF-α 48 h after H37Rv-RFP infection compared with levels in the controls (hLO alone, M. tb-infected hLO, and hLO containing hMφs)." (PMID 39052544, 2024). "TNFα levels were determined post-infection and treatment with the inhibitors." (PMID 38916198, 2024). "Measurement of chemokines in the lung showed several alterations in global IFNLR1-/- mice compared to WT mice both during super-infection and single S. aureus infection, including increased TNFα, CXCL11, CXCL12, and MIP3α and decreased IL-1β, MIP1β, and CXCL16." (PMID 39178311, 2024). "In addition, after 7 days of infection with the wild-type strain, the concentrations of the inflammation cytokines TNF-α and IL-1β in the brain tissue of mice showed a significant increase." (PMID 39240104, 2024). "Furthermore, our study provides additional details about the immunomodulatory effects of CSFV on the kinetics of CRP, TNF-α, and leukocyte sub-populations in pigs after infection with the CSFV strain Paderborn." (PMID 38393074, 2024). "Notably, the concentrations of inflammatory cytokines TNF-α, IL-1β, and IL-6 were diminished in the serum and lungs of the LysoPE-treated mice on day five post-infection." (PMID 39390593, 2024). "Furthermore, the expression of IL-1β and TNF-α was subsided with lower intensity after 48 h post-infection." (PMID 38965554, 2024). "Multiple studies have shown infection is the most common adverse event of TNF inhibitors." (PMID 39070789, 2024). "Consequently, restricted recruitment of neutrophils and TNF-α secretion will contribute to the control of the infection with homeostatic effects for the host." (PMID 39062562, 2024). "Taken together, these results suggested that intranasal boosting with the RBD-HR vaccine induced a Th1-biased cellular immune response characterized by TNF-α and IL-2 secretion, which has significant implications in the prevention of infection and limiting the spread of SARS-CoV-2." (PMID 38550714, 2024). "Furthermore, the “cytokine storm” triggered by infection, characterized by elevated levels of interleukins and tumor necrosis factor-alpha (TNF-α), likely plays a significant role in lymphocyte apoptosis." (PMID 39639950, 2024). "The authors showed that while IL-10 levels decreased, IFN-γ and TNF-α levels increased, diminishing the IL-10 production rate relative to the other two cytokines, thus favoring a pro-inflammatory effect at the late stage of infection." (PMID 38787228, 2024). "The observed effects indicate that during infection with prion strains, the pro-inflammatory cytokine TNF-α plays a role in the disease progression, although further investigation is necessary to understand its relevance for disease establishment and progression." (PMID 38790392, 2024). "Interestingly, we observed a decrease in the expression levels of TNF-α and IL-6 after 6 h of infection with 2 multiplicity of infection (MOI) Vv when pretreated with CGP57380." (PMID 38980024, 2024).
infection (continued). "Following infection of these mice, deletion of TNF signaling significantly reduced the expression of Tim3 on NK cells, both in the spleen and liver, confirming that TNF is a driver of Tim3 upregulation during S. Typhimurium infection." (PMID 39543125, 2024). "Additionally, an increase in microglial frequency and activation status, along with heightened TNFα production in response to the infection." (PMID 39959586, 2024). "At 24 h post-ex vivo infection, the median percentage differences in cytokine levels were as follows: IL-2 and IL-4 both showed no change at 0%; IL-10 exhibited a significant increase at 104%; TNF-α at 167%; and IFN-γ at 197%." (PMID 39456722, 2024). "Moreover, cytokines released by immune cells post-infection, including IL (interleukin) -6, -4, -12, -1, and tumor necrosis factor alpha (TNF-α), can contribute to the increased expression of HIF-1α." (PMID 38539163, 2024). "Five of 11 CpG sites assessed in the TNFα promoter were hypermethylated in PBMC CD8+ T cells post-SIV infection compared to pre-infection, of which only 1 CpG site at position -340 was significantly hypermethylated in intestinal compared to lymph node CD8+ T cells in SIV-infected animals." (PMID 39772149, 2024). "TNFα is involved in the regulation of infection related to S. pneumoniae serotypes." (PMID 38234660, 2024). "In addition, PVE30 reduced the secretion of the uncontrolled downstream inflammatory cytokines IL-6 and TNF-α from host cells upon infection with HSV-1." (PMID 38185640, 2024). "In the early acute phase (3–5 weeks post-infection), type 1 helper T cells (Th1) mediate the immune response by secreting cytokines such as interferon gamma (IFNγ), interleukin 1 (IL-1), and tumor necrosis factor-alpha (TNFα), targeting the migrating schistosomula." (PMID 39264964, 2024). "In addition to the activation of TLR signaling pathways, differential gene KEGG enrichment analysis also revealed a profound upregulation of genes in the TNF signaling pathway following infection." (PMID 38590438, 2024). "Previously, we observed increased intracellular TNF in AMs from APN−/− mice with IA when compared to WT AMs, and we observed mortality as early as day 2 post-infection in APN-pathway-deficient mice with IA, suggesting a critical involvement of early immune effectors in protection from infection." (PMID 38979340, 2024). "The significance of TNF-α varies with the route of infection." (PMID 38790392, 2024). "Additionally, the production of proinflammatory cytokines (TNF-α and IL-6), vital effectors mediating macrophage resistance againstBrucella infection, was augmented in the rBP26-immunized group." (PMID 38419498, 2024). "Similarly, a reduction in the severity of infection was also observed in immunocompetent animals, but only with large Aspergillus inocula, indicating that TNF-α is a critical component of innate immunity in both immunocompromised and immunocompetent hosts." (PMID 38667922, 2024). "Mediating a similar outcome, Nlrp6 (the most downregulated innate gene at 6hrs post-infection; −30.2 fold) acts as a cytosolic sensor in macrophages and mediates the secretion of pro-inflammatory cytokines IL-18, IL-1β and TNF in response to ligand stimulation." (PMID 39344634, 2024). "During an infection, tumor necrosis factor-alpha (TNF-α) is secreted." (PMID 39185035, 2024). "Infection with S. uberis induced (p < 0.01) Nrf2, HO-1, IL-6, TNF-α and Atg5." (PMID 38397769, 2024). "However, the engrafted hepatocytes have an intrinsic capacity to induce innate immune responses to stress and infection, as evidenced by their expression of several cytokines (TNF, IL6, and type I interferons) signaling pathways." (PMID 39209804, 2024). "Additionally, there was a significant increase in IL-1β, IL-6, and TNF-α levels in response to CR-hvKP57 infection, indicating varying degrees of inflammatory response." (PMID 39211794, 2024).
infection (continued). "CRP is synthesized mainly in liver cells, there is growing evidence that CRP plays an important role in inflammatory processes and host response to infection, including the complement pathway, apoptosis, and the production of cytokines, particularly interleukin-6 (IL-6) and tumor necrosis factor-α." (PMID 39720727, 2024). "NF-κB is a pro-inflammatory signaling pathway based on the activation of NF-κB proteins by pro-inflammatory cytokines such as interleukin 1 (IL-1) and tumor necrosis factor α (TNFα) that are rapidly released due to infection and activate toll-like microbial pattern recognition receptors (TLRs)." (PMID 38580623, 2024). "TNF-α plays a role in apoptosis, inflammation, and the immune response to cancer and infection." (PMID 38903796, 2024). "Moreover, this network meta-analysis provided sufficient evidence for a relationship between TNF inhibitors and infection." (PMID 39070789, 2024). "Tumor necrosis factor-alpha (TNF-α) is a potent inflammatory cytokine crucial for modulating the interplay between innate and adaptive immune responses and promotes leukocyte recruitment to the infection site through its receptors TNFR1 and TNFR2." (PMID 38932162, 2024). "However, NET formation was found to be protective in a mouse model of S. aureus skin and soft tissue infection, reflective of planktonic growth, by TNF signaling through TNFR2." (PMID 39044282, 2024). "Therefore, screening for TB prior to initiating TNF-⍺ inhibitors and annual surveillance for TB are vital in preventing serious infections in this group of patients." (PMID 38939259, 2024). "It is believed that immunological dysregulation is induced by viruses such as the herpes viruses through the infection of T-cells, leading to an excessive production of TNF-a and IFNγ, increased macrophage activation, sustained activation of CTLs, and, finally, aggressive hyperinflammatory syndrome." (PMID 39189243, 2024). "This study demonstrates the importance of TNF signaling for leukocyte recruitment during S. aureus craniotomy infection, where dramatic reductions in cellular influx were observed in the brain, galea, and bone flap of TNF KO mice during the first two weeks post-infection." (PMID 39044282, 2024). "Additionally, we observed that ASFV-WT infection inhibited the ubiquitination degradation of IκBα induced by TNF-α in PAMs." (PMID 38501350, 2024). "Pro-inflammatory cytokines such as TNF-α, IL-1β, IL-6, and IL-2 play several key roles in the brain, as follows: (i) They are crucial in initiating and regulating inflammation in response to infection, injury, or disease." (PMID 39337280, 2024). "Importantly, LTα shares 50% homology to TNF and can signal through both TNFR1 and TNFR2, possibly compensating for TNF deficiency in KO mice during craniotomy infection." (PMID 39044282, 2024). "Human infection with MPXV is associated with increased levels of ILs, C-C motif chemokine ligand 2 (CCL2) and CCL5, and a significant decrease in tumor necrosis factor alpha (TNF-α), IFN-γ, and IL-2 and IL-12." (PMID 38510963, 2024). "Moreover, there is a positive correlation between TNF-α mRNA expression with the parasite burden at week 7 and 12 post-infection." (PMID 38896633, 2024). "Moreover, macrophages secrete inflammatory cytokines such as interleukin (IL) −1, IL-2, IL-6, IFN-gamma, and tumor necrosis factor alpha (TNF-α) to combat infections." (PMID 38799158, 2024). "However, IL-6 and TNF-α had decreased (p < 0.01) at 12 hpi with NK-252 + infection compared to infection of S. uberis." (PMID 38397769, 2024). "Imad and colleagues studied the cytokine profile of 96 hospitalized adult patients admitted to the Hospital for Tropical Diseases, Bangkok, Thailand, during 2015–2016, which showed the increased expression of protein interleukins (IL-4, -6, -8, -10), TNFα, and IFNγ during infection." (PMID 39200005, 2024).
infection (continued). "Furthermore, infection and tissue injury release the pro-inflammatory cytokines, including TNF-alpha, IL-1 beta, and IL-6, which contribute to subsection increased systemic inflammatory responses." (PMID 39048980, 2024). "Infection induced an increase in TNF-α in the Ba group compared to the Ctr group (p < 0.001)." (PMID 38794208, 2024). "TNF-α, IL-1β and IL-6 are all pro-inflammatory cytokines, and they play complex roles in the inflammatory response, that can both help the host defend against infection and promote inflammation." (PMID 39176281, 2024). "Following infection with M. tb, NF-κB is activated and translocates to the nucleus, where it stimulates the expression of a range of proinflammatory cytokines, such as IL-1β, IL-6, and TNF-α." (PMID 38920649, 2024). "Interestingly, MHV-A59 stimulated TNF production in Smurf1−/− BMDMs as early as 12 h post-infection, and the levels of TNF produced by Smurf1−/− BMDMs at 48 and 72 h post-infection were five times higher than those in MHV-A59-infected wild-type BMDMs." (PMID 39452742, 2024). "Supporting the association of this inflammatory mediator on induced atrophy, the blockade of TNF, and also the reduction of oxidative stress by using an agonist of Nrf2 during early infection decreases atrogen expression and atrophic fibers while increasing weight gain." (PMID 39201595, 2024). "In addition, a significant difference between 24 and 48 hr post-infection in the expression of TNF-α (MDR [rank of difference: -0.91; P=0.03]; XDR [rank of difference: -2.88; P=0.0002]) in response to most of the resistant Mtb strains has been noticed." (PMID 38800030, 2024). "The infection may also induce the release of cytokines such as interleukin-6 and tumor necrosis factor-alpha, which contribute to gastrointestinal symptoms." (PMID 39625915, 2024). "These low levels of infection did not cause a significant inflammatory response and are comparable to the levels of IFNγ, IL1β and TNFα in un-infected tissue (Fig. 4A2c)." (PMID 38797844, 2024). "During an infection with Toxoplasma gondii, the host immune response stimulates the production of different molecules, such as interferon gamma (IFNγ), tumor necrosis factor (TNFα), and nitric oxide." (PMID 38004683, 2023). "According to their findings, none of the 10 studied anti-TNF therapies resulted in an increased risk of serious infections, malignant tumors, and tuberculosis infection compared to placebo or conventional DMARDs therapy." (PMID 37568441, 2023). "Enhanced TNF and IL-1α levels were detected in septal macrophages early post infection." (PMID 37112697, 2023). "As previous study has indicated a positive association of Blautia with key inflammatory cytokines such as TNF-α, the authors hypothesized that MD improves the inflammatory milieu and infection through modulation of gut microbiota, at least in part." (PMID 38075899, 2023). "TNF-α has a role in many events such as immunity, inflammation, tissue repair and infection." (PMID 38223592, 2023). "TNF has been one of the most studied cytokines in the course of ASFV in vivo infections." (PMID 36680273, 2023). "The M1-related cytokines, IFN-γ and TNF-α, increased and reached a peak at the 6th week post-infection (with IFN-γ higher than TNF-α), while the M2-related cytokines, IL-10 and IL-13, were boosted during the late stage of infection (with higher IL-10 than IL-13)." (PMID 36668953, 2023). "TNF-α was equally expressed at 2- and 3- months post-infection with all three parasite lines." (PMID 37539049, 2023). "Moreover, opposed to WT mice, S100A9 KO mice showed substantially increased BAL fluid levels of pro-inflammatory TNF-α and IL-1β and anti-inflammatory IL-10 on day 2 post-infection." (PMID 37467233, 2023). "Hence, immunofluorescence staining of IL-6 and TNF-α was performed to evaluate the infection levels and healing status of the wounds." (PMID 36696504, 2023).